COL1A1 (collagen type I alpha 1 chain)
Diseases named in the same sentence as COL1A1 in open-access papers (continued):
Sharing a sentence is not in itself a finding about the gene and the disease.
renal fibrosis (continued). "Further, rats that were fed the HP-HCa2+ diet expressed lower levels of four key markers of renal damage and fibrosis (NGAL, COL1A1, COL6A2, and MPG) and exhibited decreased renal fibrosis revealed by Masson’s trichrome staining to detect collagen." (PMID 32271147, 2020). "Previous studies described that TGFβ1 enhanced α-SMA, COL1A1, COL3A1, and CTGF levels to drive renal fibrosis mediated by the miR-433." (PMID 30536131, 2019). "In order to validate that miRNA-184 promoted the progression of renal fibrosis by inhibiting HIF1AN expression, qRT-PCR assay was performed to determine the expression of α-SMA, GTGF, COL1A1, and COL3A1." (PMID 30536131, 2019). "The expression of renal fibrosis markers could potentially be affected by BMP signaling, but levels of Acta2 (α-smooth muscle actin), Col1a1 and Col3a1 (type I and III collagen α1 chains), Tgfb (TGF-β1), and Fn1 (fibronectin) were not significantly changed." (PMID 40773297, 2025). "It has been reported that increased SET7/9 expression in rat mesangial cells under TGF-β stimulation promotes the expression of P21 and ECM-related genes (COL1A1, CTGF, PAI-1) by recruiting H3K4me1 enriched in the promoter regions of these genes, thereby mediating renal fibrosis." (PMID 38929505, 2024). "Of note, the increased expression level of SET7/9 can increase the promoter occupancies of H3K4me2 on the promoter of collagen type I alpha 1 (COL1A1), which may lead to ECM deposition in the kidney and renal fibrosis." (PMID 37455912, 2023). "Given the attributing role of infiltrating macrophages in inducing renal fibrosis, we assessed whether mRNA levels of the fibrosis markers α-SMA and COL1A1 were similarly reduced in qkv UUO kidneys." (PMID 34968236, 2020). "To unravel the physiological roles of PPM1K in renal fibrosis, we analyzed the RNA-sequencing dataset of a PPM1K-overexpressing HK2 cell line (GSE212681) and identified reduced expression of fibrosis-related genes such as Col1A1, Col2A1, CTGF, vimentin, and FN1 (Fig. EV3)." (PMID 40588562, 2025). "Next, the expression of RACK1 was significantly increased in fibrotic kidneys compared to that in CL kidneys and was colocalized with PDGFRα+ mesenchymal cells and αSMA+ or Col1a1+ myofibroblasts in fibrotic kidneys, implying that RACK1 may play a crucial role in FMT during renal fibrosis." (PMID 38689280, 2024). "Thus, Siglec-F+ neutrophils may contribute to renal fibrosis by 2 mechanisms, namely, by activating fibroblasts via their profibrotic cytokines (TGF-β1, TNF-α, and IL-1β) and by directly secreting COL1A1." (PMID 35482420, 2022). "Recent studies have shown that adipose-derived stem cells are able to inhibit mRNA expression levels of COL1A1, transforming growth factor β1, connective tissue growth factor and alpha actin 2 (ACTA2) in renal fibrosis tissues, thereby playing a therapeutic role in renal fibrosis." (PMID 34359971, 2021). "However, in contrast to C57Bl/6 mice, ND-13 failed to prevent renal fibrosis or to ameliorate the expression of Col1a1 in this genotype." (PMID 32987947, 2020). "Finally, gain- and loss-of-function experiments were conducted to elucidate the effect of miR-101a on the expression of Col1a1, fibronectin, α-smooth muscle actin (α-SMA), and YAP-TGF-β (transforming growth factor β)-Smad signaling pathway-related genes, as well as the degree of renal fibrosis." (PMID 32092824, 2020). "In addition, miR-101a could target and downregulate KDM3A expression, which led to elevated TGIF1, inhibited expression of Collagen I (Col1a1), fibronectin, α-SMA, YAP1, and TGF-β2 along with the extent of Smad2/3 phosphorylation, as well as delayed renal fibrosis degree." (PMID 32092824, 2020).
ovarian carcinoma (54 papers, 2014 to 2026). A malignant neoplasm originating from the surface ovarian epithelium. "ATF4 expression was associated with chemotherapy response and COL1A1 expression in ovarian cancer by IHC using tissues microarray." (PMID 40126173, 2025). "Overexpression of COL1A1 in the tumor microenvironment has been linked to metastasis in colorectal and ovarian carcinoma as well as hepatocellular carcinoma." (PMID 37592303, 2023). "Other genes such as FAP, CTSK, FBN1, THBS2, SPARC, and COL1A1 are also known to be ovarian cancer associated." (PMID 27843486, 2016). "Notably, ATF4 was associated with COL1A1 in clinical ovarian cancer tissues from TCGA and GSE156699 datasets." (PMID 40126173, 2025). "Notably, high COL1A1 expression was associated with poor survival in ovarian cancer." (PMID 40126173, 2025). "Importantly COL1A1 is both associated with CSCs and contributes to ovarian cancer chemoresistance." (PMID 25327563, 2014). "Our previous research revealed that collagen type I alpha 1 (COL1A1)-induced upregulation of lysyl oxidase-like 2 (LOXL2) was markedly overexpressed in ovarian cancer tissue samples and ascites." (PMID 41807828, 2026). "To establish a desirable cell model to explore the strategies for targeting COL1A1, we isolated CAFs and NFs from freshly dissected human ovarian cancer tissues and adjacent normal ovarian tissues, respectively." (PMID 40126173, 2025). "Collectively, these findings indicate that COL1A1 mediates chemoresistance and prognosis in ovarian cancer." (PMID 40126173, 2025). "Collectively, these results indicate that HF inhibited COL1A1 expression through mTOR‐eIF2α‐ATF4 axis in ovarian cancer CAFs." (PMID 40126173, 2025). "Based on expression of 21 CAF‐associated markers, we defined four subtypes of CAFs in ovarian cancer as follows: myofibroblast CAFs (myCAFs, 0: SMA+, 1: FAP+, 2: COL1A1+) and antigen‐presenting CAFs (apCAFs, 3: CD74+/HLA‐DRA+)." (PMID 40126173, 2025). "To evaluate the critical role of COL1A1 in ovarian cancer, we performed the following analysis using TCGA ovarian cancer dataset, GSE156699, and Kaplan‐Meier Plotter." (PMID 40126173, 2025). "In this context, recent studies in ovarian cancer demonstrated that halofuginone, a natural compound that suppresses COL1A1 production, disrupted collagen deposition, remodeled the tumor microenvironment, and improved chemosensitivity." (PMID 40851082, 2025). "Knockdown of COL1A1 in CAF2 can significantly inhibit ovarian cancer cell proliferation, migration, and invasion using a co‐culture model system." (PMID 40126173, 2025). "We cultured HOFs until they reached confluence and examined the impact of ET-1, a soluble mediator, on the expression of key ECM proteins in ovarian cancer, specifically collagen type I alpha 1 chain (COL1A1) and FN1, both of which are express by HOFs." (PMID 39985042, 2025). "Expression of α‐smooth muscle actin (α‐SMA), fibroblast activation protein (FAP), and COL1A1 is higher in CAFs than NFs by qRT‐PCR and Western blot, indicating that we successfully established ovarian cancer CAFs and NFs." (PMID 40126173, 2025). "In ovarian cancer, a high proportion of stromal cells, defined by the expression of COL1A1, was correlated with shorter survival rate of patients." (PMID 38615020, 2024). "Within the intricate milieu of ovarian cancer, Fg emerges as a dynamic orchestrator, stimulating fibroblasts to enhance the production of Type I alpha 1 collagen (COL1A1)." (PMID 38779081, 2024). "CAFs have been reported to secrete COL1A1 and facilitate the metastasis of ovarian cancer, and an oncogenic role of extracellular vesicles-encapsulated leukocyte protease inhibitor secreted by CAFs has been demonstrated in ovarian tumor progression." (PMID 36672620, 2023). "Abnormal expression of COL1A1 has been reported in several cancers, including hepatocellular carcinoma, ovarian cancer, and colorectal cancer, as well as in GC." (PMID 35368700, 2022).
ovarian carcinoma (continued). "Through further analysis of these key genes and cancer stem cell subpopulation, more critical genes can be obtained as LCP2, FCGR3A, COL1A1, COL1A2, MT-CYB, CCT5, and PAPPA, are closely associated with ovarian cancer." (PMID 35360863, 2022). "miR-29a-3p also inhibited the epithelial-mesenchymal transition in ovarian cancer through targeting on the mRNA of COL1A1." (PMID 36471281, 2022). "COL1A1 plays a central role in carboplatin resistance in ovarian cancer, acting through the ECM-receptor interaction and focal adhesion pathways." (PMID 36352420, 2022). "Similar to COL1A1, higher expression of COL3A1 was associated with shorter overall survival in patients with ovarian carcinomas." (PMID 36085041, 2022). "A collagen-remodelling gene signature containing COL1A1 and LOX is associated with the progression of ovarian cancer and unfavourable patient survival." (PMID 35004308, 2021). "COL1A1, COL11A and Thrombospondin-1 (THBS1) are indeed associated with tumour invasiveness and poor prognosis in ovarian cancer." (PMID 34238352, 2021). "In ovarian cancer cells, downregulated miR-29a/b/c enhanced the ability of cells to escape cell apoptosis induced by cisplatin via targeting collagen type I alpha 1 (COL1A1)." (PMID 34745970, 2021). "It is reported that COL1A1 is the target of miR-29, and the downregulation of miR-29 can promote the cisplatin resistance of ovarian cancer cells." (PMID 34456964, 2021). "Increased expressions of COL1A1 and COL1A2 genes were associated with lower survival of ovarian cancer patients." (PMID 32315343, 2020). "Our findings confirmed the molecular mechanism by which COL1A1-induced upregulation of LOXL2 promotes ovarian cancer metastasis through a positive feedback loop involving EGFR-MEK-ERK-SP1, offering novel scientific insights and potential therapeutic targets for inhibiting ovarian cancer metastasis." (PMID 41807828, 2026). "To further evaluate whether COL1A1 mediates chemoresistance, we pretreated 96‐well plates with 100 μg mL−1 Col1, and then seeded ovarian cancer cells SKOV3 and TOV‐21G respectively, and ultimately evaluated the IC50 value." (PMID 40126173, 2025). "Taken together, HF impairs fibrosis through inhibiting COL1A1 generation in ovarian cancer." (PMID 40126173, 2025). "ATF4 rescued COL1A1 expression under HF treatment in ovarian cancer CAF2." (PMID 40126173, 2025). "To further assess whether HF inhibits CAFs‐secreted COL1A1, we treated ovarian cancer CAFs with HF and observed that HF could inhibit the viability of CAFs in a dose‐dependent manner." (PMID 40126173, 2025). "However, studies investigating the relationship between COL1A1 expression levels and clinical characteristics of ovarian cancer (OC) remain limited." (PMID 39845977, 2024). "Also, Kyoto Encyclopedia of Genes and Genomes pathway enrichment analysis revealed that COL1A1 regulated carboplatin resistance of ovarian cancer cells through the “ECM-receptor interaction” and “focal adhesion” pathways." (PMID 35242497, 2022). "Recently it was reported that COL1A1 secreted by fibroblasts promoted stromal cells and facilitates the metastasis of ovarian cancer, which may provide a novel approach for ovarian cancer therapeutics." (PMID 33907495, 2021). "Moreover, COL1A1 accelerated intraperitoneal metastasis of ovarian cancer xenograft by intraperitoneally injection in mice." (PMID 34356118, 2021). "COL1A1 is known to promote the migration and invasion of ovarian cancer cells in vitro." (PMID 34445479, 2021). "For example, COL1A1 promotes primary ovarian cancer cell adhesion and initiates tumor growth." (PMID 33026975, 2020). "Given that COL1A1 may act as a potential therapeutic target in ovarian cancer." (PMID 40126173, 2025).
ovarian carcinoma (continued). "In addition, we further examined COL1A1 expression in ovarian cancer tissue microarray by IHC." (PMID 40126173, 2025). "In particular, THBS2, COL1A1, and COL5A1 genes are upregulated in most cancer types, except for bladder, kidney, melanoma, and ovarian cancer." (PMID 40860666, 2025). "The prognostic role of COL1A1, FN1, EDN1 (ET-1) and ARRB1 (β-arr1) gene expression was evaluated using the Kaplan–Meier plotter database and clinical ovarian cancer tissue samples." (PMID 39985042, 2025). "In ovarian cancer cells in which ITGB1 is knocked down, it reduced COL1A1-induced metastasis by partially suppressing the phosphorylation of AKT." (PMID 38963646, 2025). "A significant increase in ovarian cancer cell’s ability to attach to ECM proteins such as fibronectin and collagen type I alpha 1 chain (COL1A1) was observed upon ZNF217 overexpression." (PMID 41345234, 2025). "COL1A1, a major component of ECM, contributes to chemoresistance and poor prognosis in ovarian cancer." (PMID 40126173, 2025). "Through the analysis of stemness-related key genes and tumor stem cell subpopulations, LCP2, FCGR3A, COL1A1, COL1A2, MT-CYB, CCT5, and PAPPA are closely related to ovarian cancer." (PMID 35360863, 2022). "A previous study also showed that high expression of COL1A1, COL3A1, COL5A1, and COL5A2 in ovarian cancer promotes tumor immune tolerance and results in poor prognosis." (PMID 34034744, 2021). "Among them, collagen type I alpha 1 chain (COL1A1), a major component of ECM, was significantly upregulated in Matrix indexHigh group and resist chemotherapy, indicating that COL1A1 acts as a potential therapeutic target in ovarian cancer." (PMID 40126173, 2025). "Similar to the mesenchymal subtype from the original TCGA study of ovarian cancer, S‐ECM shows upregulation of genes such as COL5A2, COL1A1, COL3A1, THBS2, COL11A1, COL6A3, and MMP2 that are involved in epithelial‐to‐mesenchymal transformation (EMT) processes, metastasis, and chemoresistance." (PMID 36637997, 2023). "Further signalling pathways influencing COL1A1 transcription via (at least to some extent) TGFβ are Mer Tyrosine Kinase (MERTK), PKCε, Ovarian cancer G-protein coupled Receptor-1 (OGR1), β-catenin, and osteopontin (more details can be found in Appendix A, Table A5)." (PMID 37373151, 2023). "A previous study reported a negative correlation between GATA2 and COL1A1 expression in patients with breast and ovarian cancers." (PMID 36360208, 2022). "In our new analytical process, the key genes related to ovarian cancer are identified as LCP2, FCGR3A, COL1A1, COL1A2, MT-CYB, CCT5, and PAPPA, which may have important significance in ovarian cancaer and drug therapy." (PMID 35360863, 2022). "Under hypoxic stress, HIF-1 could promote the expression of COL1A1 in the mesothelial cells and the expression of LOX in both the mesothelial and cancer cells, which remodels collagen to accelerate the invasion of ovarian cancer." (PMID 35004308, 2021). "Genes COL1A1 and COL3A1 are demonstrated that played an unfavorable role in the development of ovarian cancer, and could be considered as the prognostic genes of OV." (PMID 32429941, 2020). "TRS3 and INOF cells differentiated into CAF-like cells when cultured with ovarian cancer cell conditioned medium as evidenced by the induced expression of the CAF markers ACTA2, FAP, collagen 1α (COL1A1), fibronectin (FN1), and fibronectin with an alternatively spliced domain A (FN-EDA) (p < 0.05)." (PMID 26716409, 2016). "To explore how HF regulates COL1A1 expression, we analyzed the pathway involved in COL1A1High group in ovarian cancer scRNA‐seq, and found that extracellular regulated protein kinases (ERK) and endoplasmic reticulum pathway may be involved in regulating COL1A1 expression." (PMID 40126173, 2025). "Therefore, COL1A1, COL1A2, MT-CYB, CCT5, and PAPPA may be potential genetic biomarkers for the treatment of ovarian cancer." (PMID 35360863, 2022).
ovarian carcinoma (continued). "COL1A1 and COL1A2 may be involved in the occurrence and metastasis of ovarian cancer." (PMID 35360863, 2022). "From the total of 34 ligand and receptor genes identified in these interactions, seven (COL1A1, ITGB5, COL1A2, FGFR2, FN1, IGF1, and IGF2) were consistently up-regulated and predicted worse overall survival in two additional cohorts (TCGA and GSE9891) of ovarian cancer patients." (PMID 36352420, 2022). "COL1A1 is a type of collagen (COL) that has been reported to be upregulated in ESCC and may contribute to paclitaxel and topotecan resistance in ovarian cancer cells." (PMID 34456964, 2021). "It is also noticed that the origins of high COL1A1, COL1A2, and COL3A1 expression positively correlate with fibroblast-specific markers (FAP) and smooth muscle actin (ACTA2), whereas COL4A1, COL4A2, and COL18A1 seem to be predominantly expressed in ovarian cancer cells." (PMID 33026975, 2020).